DDX5 (DEAD-box helicase 5)
Description:
Involved in the alternative regulation of pre-mRNA splicing; its RNA helicase activity is necessary for increasing tau exon 10 inclusion and occurs in a RBM4-dependent manner. Binds to the tau pre-mRNA in the stem-loop region downstream of exon 10. The rate of ATP hydrolysis is highly stimulated by single-stranded RNA. Involved in transcriptional regulation; the function is independent of the RNA helicase activity. Transcriptional coactivator for androgen receptor AR but probably not ESR1. Synergizes with DDX17 and SRA1 RNA to activate MYOD1 transcriptional activity and involved in skeletal muscle differentiation. Transcriptional coactivator for RUNX2 and involved in regulation of osteoblast differentiation. Acts as a transcriptional repressor in a promoter-specific manner; the function probably involves association with histone deacetylases, such as HDAC1. As component of a large PER complex is involved in the inhibition of 3' transcriptional termination of circadian target genes such as PER1 and NR1D1 and the control of the circadian rhythms.
Synonyms: G17P1; HLR1; p68; HUMP68
Tractability: Small molecule: a structure with a bound ligand is known. PROTAC: UniProt records ubiquitination sites on it; ubiquitination databases record sites on it; its protein half-life has been measured; a small molecule that binds it is known.
Target class: Enzyme; Hydrolase
Gene: Protein-coding gene on chromosome 17 (64,498,254 to 64,508,199, reverse strand). Ensembl gene ENSG00000108654.
Subcellular location: Nucleus; Nucleus, nucleolus; Nucleus speckle; Cytoplasm
Subcellular location (Human Protein Atlas): Nucleoli; Nucleoplasm
Pathways (Reactome):
Disease: Dengue Virus-Host Interactions; Replication of the SARS-CoV-1 genome; Replication of the SARS-CoV-2 genome
Metabolism of RNA: mRNA Polyadenylation; mRNA Splicing - Major Pathway
Metabolism of proteins: SUMOylation of transcription cofactors
Signal Transduction: Estrogen-dependent gene expression
Gene Ontology:
Molecular function: MH2 domain binding; mRNA 3'-UTR binding; nuclear androgen receptor binding; pre-mRNA binding; primary miRNA binding; protein binding; R-SMAD binding; ribonucleoprotein complex binding; RNA binding; RNA helicase activity; SMAD binding; promoter-specific chromatin binding; ATP binding; ATP hydrolysis activity; calcium-dependent protein binding; calmodulin binding; enzyme binding; nucleic acid binding
Biological process: alternative mRNA splicing, via spliceosome; androgen receptor signaling pathway; BMP signaling pathway; epithelial to mesenchymal transition; estrogen receptor signaling pathway; mRNA transcription; negative regulation of transcription by RNA polymerase II; nuclear-transcribed mRNA catabolic process; primary miRNA processing; regulation of alternative mRNA splicing, via spliceosome; regulation of androgen receptor signaling pathway; regulation of miRNA transcription; regulation of transcription by RNA polymerase II; miRNA transcription; mRNA splicing, via spliceosome; myoblast differentiation; regulation of osteoblast differentiation; regulation of skeletal muscle cell differentiation; regulation of viral genome replication
Cellular component: catalytic step 2 spliceosome; cytoplasm; extracellular exosome; membrane; nuclear speck; nucleolus; nucleoplasm; nucleus; ribonucleoprotein complex; cytosol
Genetic constraint (gnomAD): Loss-of-function variants: 6 observed, 67.07 expected, observed/expected ratio (o/e) 0.0895, 90% interval 0.048 to 0.18. The synonymous counts are far from expectation, so gnomAD's model fits this gene poorly and the ratio says little. Missense variants: 492 observed, 780.02 expected, observed/expected ratio (o/e) 0.63, 90% interval 0.58 to 0.68. Synonymous variants: 346 observed, 257.46 expected, observed/expected ratio (o/e) 1.34, 90% interval 1.23 to 1.47.
Cancer hallmarks: invasion and metastasis (promotes); proliferative signalling (promotes); escaping programmed cell death (promotes)
Homologues: Orthologues: chimpanzee DDX5 (100% identical), dog DDX5 (100% identical), guinea pig DDX5 (99% identical), mouse Ddx5 (99% identical), macaque DDX5 (98% identical), pig DDX5 (98% identical), rat Ddx5 (98% identical), rabbit DDX5 (98% identical), tropical clawed frog ddx5 (82% identical), zebrafish ddx5 (76% identical). Paralogues in human: DDX17 (69% identical), DDX42 (36% identical), DDX3X (35% identical), DDX3Y (35% identical), DDX43 (34% identical), DDX53 (33% identical), DDX4 (30% identical), DDX41 (30% identical), DDX46 (30% identical), DDX23 (28% identical), DDX59 (25% identical), DDX21 (25% identical), and 26 more.
Diseases named in the same sentence as DDX5 in open-access papers:
DDX5 is named in the same sentence as 133 diseases in open-access papers, as found by Europe PMC text mining. Sharing a sentence is not in itself a finding about the gene and the disease. The quoted sentences say what the papers report.
breast carcinoma (42 papers, 2011 to 2026). "SRSF1 interacts with Thrap3 (thyroid hormone receptor associated protein 3) and DDX5, which promote R-loop resolution in breast cancer cells." (PMID 35954483, 2022). "The DDX5 protein also regulates the expression of genes encoding DNA replication factors in breast cancer cells and has been suggested to play a role in the responses to chemotherapy and radiotherapy." (PMID 30678233, 2019). "The Wnt-β-catenin/TCF4 signaling pathway was found to be abnormally activated in colon and breast cancers and associated with a poor prognosis, suggesting the potential of DDX5 as a valuable diagnostic and prognostic marker and potential therapeutic target for many tumors." (PMID 38612503, 2024). "It is reported that, in several breast cancer cell lines, DDX5 is over-expressed and down regulation of DDX5 expression reduced expression of growth-related E2F target genes and suppressed proliferation of the cancer cells." (PMID 40869977, 2025). "The expression and prognostic value of RBPs ZC3H12D (zinc finger CCCH domain‐containing protein 12D) and DDX5 (DEAD box protein 5) in breast cancer were analyzed in public databases and tumor samples." (PMID 41263459, 2025). "The expression of ZC3H12D and DDX5 was reduced and increased in human breast cancer tissues, respectively, and was closely related to the prognosis of breast cancer patients." (PMID 41263459, 2025). "Enhanced expression of DDX5 is often observed in several types of cancers, such as colon, prostate, and breast cancers and is believed to contributes to proliferation of cancer cells by facilitating growth-related gene expression." (PMID 40869977, 2025). "We first silenced DDX5 mRNA and performed qRT-PCR tests in breast cancer cells, which showed that the down-regulation of DDX5 reduced levels of SNHG15." (PMID 39519115, 2024). "It has been reported that the DDX5 locus is frequently amplified in breast cancers and that over-expressed DDX5 facilitates cell growth by directly binding to E2F1 to increase the expression of E2F target genes involved in DNA replication." (PMID 39769018, 2024). "DDX5 is frequently over-expressed in colon, prostate, and breast cancers, and knockdown of both DDX5 and DDX17, which shows high homology to DDX5, impairs cancer cell proliferation." (PMID 39769018, 2024). "Many studies have shown that DDX5 is aberrantly expressed and plays an oncogenic role in nearly all types of cancers, including colon cancer, breast cancer, and prostate cancer." (PMID 38136426, 2023). "As an oncogene, DDX5 is overexpressed in many tumours, promoting tumour cell growth and metastasis, including cancers of the breast, colon, prostate, non-small cell lung cancer (NSCLC) and glioma." (PMID 36996491, 2023). "High levels of DDX5 have been reported in breast cancer previously and DDX5 has been considered as a hopeful therapeutic candidate for DDX5-amplified breast tumors." (PMID 38040691, 2023). "The current literature underscores the oncogenic role DDX5 plays in almost all types of cancers, including lung, colon, and breast cancers." (PMID 38136426, 2023). "DDX5 is frequently amplified in breast cancer and is closely coupled with the proliferation of cancer cells." (PMID 36996491, 2023). "DDX5 is essential for the transcriptional activation of FRA-1 target genes, and both positively and negatively regulated DDX5-dependent gene sets exhibit prognostic value in breast cancer patients." (PMID 37176013, 2023). "A previous study reported the observation that MCM2, MCM5 and CDC45 proteins are all downregulated in DDX5-depleted breast cancer cells; however, the role of the direct interaction between DDX5 and MCM5 in the regulation of MCM5 levels is presently unclear." (PMID 35954483, 2022). "Since DDX5 acts as an oncogene in breast cancer, the significance of the interaction with DDX5 is unclear, since it was reported that the RNA helicases DDX5 and DDX17 are positive regulators of the transcription activity of MYOD1." (PMID 35954483, 2022).
breast carcinoma (continued). "and endoxifen and fulvestrant, which are endocrine therapy drugs, inhibit breast cancer by downregulating DDX5/DDX17 expression." (PMID 35992805, 2022). "DDX5 expression has been found to increase progressively from luminal to basal cells in breast cancer, with a concomitant expression of CD44." (PMID 35954483, 2022). "In breast cancer, DDX5/DDX17, auxiliary activators of ERα, are recruited to the ERα-responsive promoter to promote gene transcription." (PMID 35992805, 2022). "The most prevalent genes that were differentially altered in recurrent tumors were the known oncogene DDX5, which has been shown to be frequently amplified in breast cancers, and CCNE1, which is frequently amplified in HGSOC." (PMID 35883104, 2022). "In early-stage breast cancer, DDX5 expression along with overexpression of EGFR and Ki67, a nuclear marker for cell proliferation, positively correlates with a poor prognosis and invasiveness of tumors, a high risk of recurrence and worse survival in patients." (PMID 35954483, 2022). "High DDX5 expression increases the recurrence rates of breast cancer, hepatocellular carcinoma, glioma, and squamous cell carcinoma, shortening the clinical survival time." (PMID 35992805, 2022). "In our study, we verified the interaction between DDX3X/DDX5 and Ring1b, and confirmed the function and mechanism of these complexes in breast cancer metastasis." (PMID 33608512, 2021). "In this study, DRD2 was confirmed to suppress tumorigenesis if breast cancer through interacting with DDX5 and eEF1A2." (PMID 33859743, 2021). "With mass spectrometry and immunoprecipitation analysis, three potential TRIB3-interacting proteins were identified and two of them, BCLAF1 and DDX5, served as poor prognostic factors in breast cancer patients at the protein level." (PMID 30678233, 2019). "Based on the data of The Human Protein Atlas, BCLAF1 and DDX5 had an unfavorable prognostic factor among breast cancer patients, although only BCLAF1 reached statistical significance." (PMID 30678233, 2019). "In breast cancer, DDX5 correlated strongly with Ki67, a nuclear marker for cancer cell proliferation indicating poor prognosis and high invasiveness." (PMID 28216662, 2017). "Second, we observed that many of the Ddx5/17 splicing-regulated genes have been reported to play a direct role in tamoxifen resistance, one of the major endocrine therapies of breast cancer." (PMID 24275493, 2014). "Nuclear accumulation of β-catenin is important for cancer development and it is found to overlap with p68 (DDX5) immunoreactivity in most breast cancers, as indicated by both clinical investigations and studies in cell lines." (PMID 25499975, 2014). "Another previous experimental data also indicated that DDX5 plays a role in reorganization of actin cytoskeleton in breast cancer." (PMID 25150365, 2014). "To determine whether DDX5 expression was correlated with human breast cancer aggressiveness, we analyzed different human breast cancer datasets." (PMID 41263459, 2025). "DDX5 expression is abnormally high in human breast cancers and can promote tumor progression." (PMID 41263459, 2025). "Moreover, it was demonstrated in breast cancer cells that lncRNA MACC1-AS1 can form a complex with DEAD-Box Helicase 5 (DDx5), recruiting Specificity Protein 1 (SP-1) to the MACC1 core promoter and ultimately leading to an increase in MACC1 expression." (PMID 39580452, 2024). "In addition to this feature, aberrant modifications of DDX5 leading to tumor progression have been observed in diverse human cancers, including breast cancer, colon cancer, prostate cancer and glioma." (PMID 38040691, 2023). "In this study, we analysed RNA-seq data in HNRNPU knockout and DDX5 knockdown breast cancer cells." (PMID 36347834, 2022).
breast carcinoma (continued). "The identification of KIF23 as a direct interactor of DDX5 might suggest that a similar mechanism could be present in breast cancer cells." (PMID 35954483, 2022). "Considering the oncogenic role of DDX5 in breast cancer, the overexpression of DDX5 could be crucial for limiting the oncosuppressive action of AKAP8 through its nuclear sequestration." (PMID 35954483, 2022). "In breast cancer, sumoylation is overactivated and increases the stability of DDX5 and DDX17, which may explain the high DDX5/DDX17 expression in breast cancer." (PMID 35992805, 2022). "The results of CPTAC revealed that the total expression of DDX5 protein was considerably higher in eight cancer types, including ovarian cancer, breast cancer, GBM, HNSC, UCEC, LUAD, colon cancer, and hepatocellular carcinoma, compared to that of matched normal tissues (p < 0.001)." (PMID 36313454, 2022). "Last, DDX5 has been implicated in several tumors (e.g., NSCLC, breast cancer, gastric cancer, multiple myeloma, glioma) through aberrant expression or through the regulation of proliferation, metastasis, and invasion pathways that directly regulate oncogenesis." (PMID 34207140, 2021). "Importantly, the overexpression of DDX5 in breast cancer has been observed, validating the therapeutic value of targeting the helicase activity of DDX5." (PMID 32747416, 2020). "DDX5 was highly expressed in a high proportion of breast cancers." (PMID 31206546, 2019). "Additionally, DDX5 protein expression was higher in all stages of breast cancer." (PMID 41263459, 2025). "Since DDX5 has been elucidated to have a well-defined mechanism of action in tumors including breast cancer by reviewing the literature, we established DDX5 as a reciprocal target and further examined whether AURKAIP1 fostered TNBC development via the DDX5 mediator." (PMID 38040691, 2023). "We investigated the degree of DDX5 protein phosphorylation in 12 cancer types, and the results demonstrated a high degree of phosphorylation at the S430 locus in primary tumors compared to normal matched controls in breast cancer and HNSC, which contributes to the diagnosis and prognosis of cancer." (PMID 36313454, 2022). "Thus, it might be hypothesized that DDX3X and DDX5 exert their tumor-promoting functions in breast cancer by enhancing the expression/activity of oncogenes and repressing oncosuppressors." (PMID 35954483, 2022). "These PAK5-mediated modifications consequently increase oncogenic miR-10b biogenesis by augmenting the interaction of DDX5 with the Drosha-DGCR8 complex, facilitating pri-miR-10b cleavage and maturation in breast cancer." (PMID 38689093, 2024). "The phosphorylation of DDX5 increased at the S480 residue in HNSC and breast cancer tissues compared to that of normal matched tissues (p < 0.05)." (PMID 36313454, 2022). "DDX5 is also a co-activator of β-catenin, and it has been shown to be involved in Wnt pathway-mediated expression of TCF4 in breast cancer cells." (PMID 35954483, 2022). "T69-phosphorylated DDX5 by PAK5 increases binding to the Drosha/DGCR8 complex to facilitate miR-10b production, promoting breast cancer cell proliferation and migration." (PMID 35992805, 2022). "Our CHIP-seq and CHIP-qPCR data showed a similar pattern in breast cancer cells.: HNRNPU and DDX5 are enriched in the TSS of LMO4 and then activate LMO4 transcription." (PMID 36347834, 2022). "However, the mechanism underlying the oncosuppressor role of MYOD1 in breast cancer has not been discovered yet, so investigating its interaction with DDX5 might provide some clues about the molecular pathways involved." (PMID 35954483, 2022). "In line with previous findings, down-regulation of DDX5, DDX17, and DGCR8 transcript levels in breast cancer was observed." (PMID 34117091, 2021).